SPACA9 (sperm acrosome associated 9)
Description:
Microtubule inner protein (MIP) part of the dynein-decorated doublet microtubules (DMTs) of multiciliated respiratory cells and the distal singlet microtubules of monoflagellated spermatozoa. Forms an extensive interaction network cross-linking the lumen of axonemal doublet microtubules (By similarity).
Synonyms: C9orf9; Mast
Tractability: Small molecule: a structure with a bound ligand is known. PROTAC: ubiquitination databases record sites on it.
Gene: Protein-coding gene on chromosome 9 (132,878,027 to 132,890,201, forward strand). Ensembl gene ENSG00000165698.
Subcellular location: Cytoplasm; Cytoplasmic vesicle, secretory vesicle, acrosome; Cytoplasm, cytoskeleton, cilium basal body; Cytoplasm, cytoskeleton, flagellum axoneme; Cytoplasm, cytoskeleton, cilium axoneme; Nucleus
Subcellular location (Human Protein Atlas): Vesicles; Cytosol; End piece
Gene Ontology:
Molecular function: microtubule binding; protein binding; calcium-dependent protein binding
Biological process: axoneme assembly; flagellated sperm motility
Cellular component: axonemal microtubule; axoneme; cytoplasmic microtubule; cytosol; sperm end piece; acrosomal vesicle; axonemal microtubule doublet inner sheath; ciliary basal body; ciliary base; cytoplasm; nucleus; sperm flagellum
Genetic constraint (gnomAD): Loss-of-function variants: 15 observed, 13.5 expected, observed/expected ratio (o/e) 1.11, 90% interval 0.74 to 1.68. The upper end of that interval is the gene's LOEUF score, 1.68, which puts it in group 6 of 6, group 1 being the genes least tolerant of losing a copy. Missense variants: 292 observed, 304.55 expected, observed/expected ratio (o/e) 0.96, 90% interval 0.87 to 1.06. Synonymous variants: 111 observed, 118.82 expected, observed/expected ratio (o/e) 0.93, 90% interval 0.8 to 1.09.
Homologues: Orthologues: chimpanzee SPACA9 (98% identical), macaque SPACA9 (95% identical), dog SPACA9 (86% identical), rabbit SPACA9 (86% identical), rat Spaca9 (83% identical), mouse Spaca9 (68% identical), guinea pig SPACA9 (66% identical), pig SPACA9 (66% identical), tropical clawed frog spaca9 (47% identical), zebrafish spaca9 (41% identical).
Diseases named in the same sentence as SPACA9 in open-access papers:
SPACA9 is named in the same sentence as 14 diseases in open-access papers, as found by Europe PMC text mining. Sharing a sentence is not in itself a finding about the gene and the disease.
SPACA9 shares sentences with these, for which no sentence is quoted: bladder cancer (1 paper); bladder transitional cell carcinoma (1); cancer (1); colon polyps (1); colorectal cancer (1); digestive tumors (1); esophageal cancer (1); gastric cancer (1); lentivirus infection (1); liver cancer (1); pancreatic cancer (1); rectum cancer (1); squamous cell lung carcinoma (1); tumor (1).